FBN1 (fibrillin 1)
Diseases named in the same sentence as FBN1 in open-access papers (continued):
Sharing a sentence is not in itself a finding about the gene and the disease.
aortic aneurysm (continued). "Disruption of genes coding for components of the TGF-β signaling pathway or its interactors, such as fibrillin-1, have recently been described in patients with aortic aneurysm." (PMID 25608574, 2015). "GrB contributes to aortic aneurysm via an extracellular mechanism involving the cleavage of the microfibrillar protein fibrillin-1." (PMID 22479366, 2012). "Defective fibrillin-1 disrupts connective tissue integrity, leading to characteristic features such as tall stature, long limbs, flexible joints, lens dislocation, and serious cardiovascular complications, including aortic aneurysms and dissections." (PMID 41411243, 2025). "MFS is caused by mutations in the Fbn1 gene, leading to increased TGF-β signaling, reduced smooth muscle contractility, and impaired endothelial function, all of which contribute to the development of aortic aneurysms." (PMID 39684412, 2024). "A 3’UTR mutation in FBN1 was identified in patients with MFS, the molecular mechanism of which suggests the involvement of endoplasmic reticulum stress responses in the formation of aortic aneurysms." (PMID 38317175, 2024). "FBN1 null mice die perinatally because of ruptured aortic aneurysm." (PMID 38269088, 2023). "In addition, circulating fragments of fibrillin-1 may be biomarkers for aortic aneurysm and dissection." (PMID 28708846, 2017). "Due to Fbn1-pathological variants, latent TGF-β binding proteins fail to retain this cytokine in the ECM (fibrillin-1 microfibrils), leading to persistently abnormal TGF-β hypersignaling and aortic aneurysm formation." (PMID 40349485, 2025). "In addition, we showed that 17β-estradiol promotes fibrillin-1 production in human aortic smooth muscle cells and suggest that compounds that increase fibrillin-1 production in a Marfan diseased aorta may have therapeutic potential for aortic aneurysms." (PMID 28708846, 2017). "A total of 115 patients with suspected MFS or early-onset aortic aneurysm/dissection, who had a negative result in a 15-gene panel testing, were included in this study and evaluated for gross deletions and duplications in FBN1 and TGFBR2 gene by MLPA assay." (PMID 30286810, 2018). "Recently, a missense mutation in TGFβR2 identical to the one found in MFS patients who tested negative for mutation in FBN1 was found in a patient with BAV and aortic aneurysm but an earlier study found no mutation in either TGFBR1 or TGFBR2 in patients with isolated BAV." (PMID 22701807, 2012).
Aortic dissection (34 papers, 2009 to 2026). Aortic dissection refers to a tear in the intimal layer of the aorta causing a separation between the intima and the medial layers of the aorta. "Relative risk analysis indicated that patients with FBN1 mutations were 3.0 times more likely to develop aortic dissections (RR 3.0, 95% CI 2.2–4.1)." (PMID 40110250, 2025). "Genetically, MFS is caused by mutations in the FBN1 gene, leading to fibrillin-1 deficiency, which induces abnormalities in elastic fiber structure and weakened vascular wall integrity, substantially increasing the risk of aortic dissection." (PMID 40680508, 2025). "The lifetime risk of aortic dissection in FBN1 mutation carriers was 21%, compared to 7% in the general population." (PMID 40110250, 2025). "The propensity for aortic dissection in MS is particularly heightened in individuals who harbor specific FBN1 gene mutations." (PMID 38050214, 2023). "This subgroup of patients with MFS experiences increased the risks of dilatation of the ascending aorta, aortic dissection, and pejorative FBN-1 gene mutation, thus, advocating for complete arterial screening and specific follow-up." (PMID 35360038, 2022). "At the same time, it is believed that FBN1 gene mutation, which the main factor leading to patients with aortic dissection or aneurysm, and double mutation sites are a crucial factor that aggravates the patient’s phenotype." (PMID 33200202, 2020). "We found that a high proportion of aortic dissection in MFS patients with FBN1 nonsense and frameshift mutations, predicting that patients with nonsense and frameshift mutations are more prone to aortic dissections." (PMID 31830381, 2020). "Individuals with specific FBN1 mutations may have a more aggressive disease course with a higher risk of aortic dissection." (PMID 38050214, 2023). "In FinnGen PheWeb, this FBN1 haplotype was associated with aortic dissection." (PMID 34469433, 2021). "Patients with PTC variants in the FBN1 gene had more severe aortic phenotypes than those with in-frame variants, including a higher risk of aortic dissection (11% vs. 7%) or surgery (25% vs. 17%), and a larger mean aortic root diameter, despite younger age (suggesting faster aortic root dilation)." (PMID 33731877, 2021). "At the gene level association using the SKAT test with variants weighted by CADD score (Combined Annotation Depletion Dependent), standing/sitting height ratio, systolic and diastolic BP, subcutaneous adipose tissue, and aortic dissection were significantly associated with FBN1." (PMID 33226994, 2020). "Transcriptome analysis revealed that the messenger RNA expression of RNF213 was linked with that of FBN1, the most frequent pathogenetic gene in aortic dissection, suggesting that reduced RNF213 expression might be associated with the interruption of aortic development." (PMID 35455046, 2022). "This FBN1 variant was reported to associate with MFS and familial thoracic aortic aneurysm and aortic dissection (TAAD)." (PMID 35207686, 2022). "A potentially clinically relevant finding is the identification of a linkage group of SNPs encompassing the FBN1 gene, which is associated with TAA in the UK Biobank and with aortic dissection in FinnGen cohorts." (PMID 34469433, 2021). "A different model of aortic dissection/aneurysm using fibrillin-1 knockout mice contributes to the development of thoracic aortic dissection/aneurysm with increase in transforming growth factor beta (TGF-β) pathway activity." (PMID 31341173, 2019). "In this study, we report a young nonsyndromic male with aortic dissection carrying two missense variants of unknown significance in MYLK and FBN1, whose segregation analysis helped evaluate their pathogenicity and was useful for genetic counseling in the proband and his families." (PMID 39185084, 2024).
Aortic dissection (continued). "In addition, patients with thoracic aortic aneurysm who developed acute or subacute aortic dissection were more likely to have higher fibrillin-1 fragment levels than thoracic aortic aneurysm patients without dissection, indicating a more severe aortic involvement." (PMID 34059089, 2021). "Nine proteins (Lumican, FGL1, PI16, MMP9, FBN1, MMP2, VWF, MMRN1, and PF4) related to the pathogenesis of aortic dissection were identified by David /Ease and String techniques as candidate biomarkers for verification test." (PMID 35910577, 2022). "In patients in whom no mutations in FBN-1 and TGFβ were found, homozygous deletions in the COL3A1 gene have been identified, and these mutations lead to structural alterations of the collagen that could cause aortic dissection." (PMID 32273946, 2020).
thoracic aortic aneurysm (32 papers, 2014 to 2026). An aneurysm formed in the wall of the proximal portion of the descending aorta proceeding from the arch of the aorta. "Background/Objectives: Thoracic aortic aneurysms have long been associated with germline mutations such as FBN1, TGFBR2, and COL3A1, which predispose to Marfan, Loeys-Dietz, and Ehlers-Danlos syndromes, respectively." (PMID 42074482, 2026). "A mere three years later, it was reported in three simultaneous studies that mutations to the gene FBN1 that encodes fibrillin-1 predispose to thoracic aortic aneurysm and subsequent dissection and rupture." (PMID 39830801, 2025). "Most pathogenic or likely pathogenic variants of FBN1 exon 11 currently registered in ClinVar are nonsense or frameshift variants found in patients with MFS or family/isolated thoracic aortic aneurysms." (PMID 39939800, 2025). "The cardiac clinical presentation of WMS patients caused by mutations in FBN1 includes thoracic aortic aneurysm and cervical artery dissection." (PMID 37240210, 2023). "Some recent researches also indicated that variants of FBN1 was strongly related to the developing of thoracic aortic aneurysm or dissection (TAAD) in addition to MFS." (PMID 35307021, 2022). "Moreover, in our work, all the identified VUSs were missense variants, consistent with a report on French patients with nonsyndromic thoracic aortic aneurysms and dissections, where the disease was associated with only missense variants in the FBN1 gene." (PMID 39125885, 2024). "FBN1 mutations in the aorta cause the formation of loose and disordered elastic fibers, leading to a weakened vascular wall and the consequent early formation of thoracic aortic aneurysms (TAAs)." (PMID 37894814, 2023). "Interestingly, this haplotype, as illustrated by the FBN1 intronic variant rs1561207, demonstrated a pronounced dose-dependence: homozygotes had significantly higher prevalence of thoracic aortic aneurysm than heterozygotes." (PMID 34469433, 2021). "Linkage group of FBN1 variants associated with thoracic aortic aneurysm." (PMID 34469433, 2021). "Common variants of the MYH11 gene are associated with CAD and high blood pressure, and SNPs in the FBN1 gene correlate with thoracic aortic aneurysm, coronary artery dissection, and blood pressure, according to the GWAS Catalog." (PMID 39125885, 2024). "Thoracic aortic aneurysms and cervical artery dissection were reported in a three-generation family with FBN1-related WMS." (PMID 37240210, 2023). "A previous study revealed that two single nucleotide polymorphisms (SNPs, rs2118181 and rs10519177) in the FBN-1 gene were associated with thoracic aortic dissection (TAD), thoracic aortic aneurysm (TAA), and TAAD." (PMID 35307021, 2022). "It is also known that BAV is more frequent in patients with thoracic aortic aneurysm (TAA) related to mutations in ACTA2, FBN1, and TGFBR2 genes." (PMID 28883797, 2017). "A recent genome wide association study (GWAS) found that two single nucleotide polymorphisms (SNPs, rs2118181 and rs10519177) in the FBN-1 gene were associated with TAD, TAA, and thoracic aortic aneurysm or dissection (TAAD)." (PMID 24743685, 2014). "The proband and the uncle had a positive thoracic aortic aneurysm and dissection (TAAD) panel for MFS revealing an FBN1 deletion." (PMID 41815795, 2026). "Although the endophenotype of thoracic aortic aneurysm is present in many individuals with pathogenic variants in FBN1, that phenotypic manifestation alone is not a specific predictor for pathogenic variants in FBN1, being associated with at least five other loci." (PMID 38103548, 2024).
ovarian carcinoma (28 papers, 2013 to 2025). A malignant neoplasm originating from the surface ovarian epithelium. "A few studies reveal that FBN1 is a risk factor for hematogenous and lymphatic metastasis in serous ovarian cancer and promotes chemoresistance in ovarian cancer organoids." (PMID 36119108, 2022). "Of note, the data presented from cBioportal in our study, indicate that six FBN1 mutations were present in patients with ovarian cancer, with one of the missense mutations located in the coding region for asprosin." (PMID 34386072, 2021). "In our previous covariate-adjusted single-gene analyses of 3769 ovarian cancer patients, FBN1 was identified as the top gene associated with poor overall survival, suggesting that it might have a functional role in ovarian cancer progression." (PMID 41008788, 2025). "FBN1 expression is strongly associated with desmoplasia in ovarian cancer." (PMID 36134026, 2022). "In this context, investigating the expression of both FBN1 and the novel glucogenic hormone asprosin in human ovarian tissues will enhance our understanding of the underlying molecular mechanisms implicated in ovarian cancer, as well as the regulation of its tumour microenvironment." (PMID 34386072, 2021). "FBN1 is enriched in the mesenchymal (desmoplastic) molecular subtype of ovarian cancer and is primarily expressed in ovarian fibroblasts and the fibroblast-secreted ECM." (PMID 41008788, 2025). "A recent report indicated that chemoresistance in ovarian cancer is mediated through a FBN1/VEGF/STAT2 signaling axis." (PMID 41440237, 2025). "In previous studies, the Fibrillin-1/VEGFR2/STAT2 signaling axis promoted cisplatin chemoresistance via modulating glycolysis in ovarian cancer cells." (PMID 38184549, 2024). "In ovarian cancer, RNA-seq demonstrates that FBN1 is highly expressed in cisplatin-resistant ovarian cancer." (PMID 38269088, 2023). "FBN1 is highly expressed in gastric cancer, colorectal cancer, osteosarcoma, papillary thyroid carcinoma, renal cell carcinoma and ovarian cancer." (PMID 38269088, 2023). "Meanwhile, FBN1 has been identified as a prospective biomarker to assess overall survival and progression-free survival in ovarian cancer patients." (PMID 38269088, 2023). "Consistently, there is a significant correlation between FBN1 and ovarian cancer prognosis, and high level of FBN1 leads to poor prognosis in ovarian cancer patients." (PMID 38269088, 2023). "FBN1 (fibrillin-1) has been reported to enhance the cisplatin resistance of ovarian cancer by being involved in angiogenesis and glycolysis." (PMID 36424614, 2022). "The expression distribution of 6-OMAGs mRNA in 45 human ovarian cancer cell lines obtained from the CCLE dataset demonstrated that there were large variations in the expression levels of FBN1, TIMP3, and UCHL1 between cell lines." (PMID 36424614, 2022). "Our data corroborates the previous findings, as it demonstrates that the mRNA expression of FBN1 was significantly lower in patients with ovarian cancer compared to healthy volunteers (n=6)." (PMID 34386072, 2021). "The present study investigated the expression levels of the glucogenic hormone asprosin [encoded by fibrillin-1 (FBN1)], and its cognate receptor, olfactory receptor 4M1 (OR4M1), in ovarian cancer." (PMID 34386072, 2021). "As noted in the clinical ovarian cancer samples, these human ovarian cancer cell lines exhibit relatively lower FBN1 expression compared with the normal ovarian tissue." (PMID 34386072, 2021). "RT-qPCR revealed expression levels of OR4M1 and FBN1 in clinical samples and in ovarian cancer cell lines (SKOV-3, PEO1, PEO4 and MDAH-2774), as well as the normal human ovarian surface epithelial cell line (HOSEpiC)." (PMID 34386072, 2021).
ovarian carcinoma (continued). "The methylation status of FBN1 within the ovarian cancer data set appears to be highly variable compared to other cancers, as indicated by the beta value of ~0.5; however, there is a lack of comparable normal data for ovarian cancer from TCGA." (PMID 34386072, 2021). "FBN1, fibrillin-1, is an extracellular matrix molecule which has been shown to promote ovarian cancer metastasis." (PMID 29215599, 2017). "According to previous studies on ovarian cancer biomarkers, FBN1 and MMP2 were found to be metastasis-promoting markers that were stimulated or suppressed by Aurora-A or BRCA2." (PMID 28562334, 2017). "Other genes such as FAP, CTSK, FBN1, THBS2, SPARC, and COL1A1 are also known to be ovarian cancer associated." (PMID 27843486, 2016). "The tumor array validation indicates that FBN1 can serve as a biomarker for predicting recurrence of platinum-sensitive ovarian cancer." (PMID 23555212, 2013). "We further validated the role of FBN1 in ovarian cancer recurrence using tumor microarrays (TMAs) consisting of a cohort of 78 independent patients (see Section Materials and Methods)." (PMID 23555212, 2013). "Furthermore, increased FBN1 expression in cisplatin-resistant ovarian cancer models indicates that the Fibrillin-1/VEGFR2/STAT2 axis plays a regulatory role in glycolysis and angiogenesis, thereby contributing to cisplatin resistance." (PMID 40191206, 2025). "FBN1 expression was significantly enhanced in cisplatin-resistant ovarian cancer organoids, showing that FBN1 might be a relevant factor in the chemoresistance of ovarian cancer." (PMID 37046719, 2023). "Moreover, in ovarian cancer, fibrillin-1 (FBN1) knockdown enhances cisplatin sensitivity by inhibiting glycolysis and angiogenesis." (PMID 36900384, 2023). "Moreover, FBN1 expression was detected in the human ovarian cancer cell line SKOV-3, the high-grade serous PEO1 and PEO4 cell lines, and the human endometroid ovarian cancer cell line MDAH-2774, as well as the normal ovarian epithelial cells (OSE)." (PMID 34386072, 2021). "In our study, high FBN1 expression predicts lower overall- and progression-free survival of patients with late stages (i.e., III and IV) of ovarian cancer, corroborating previous findings which show promising prognostic potential of FBN1 as part of a panel of genes." (PMID 34386072, 2021). "In particular, FBN1, which was detected as a signature gene of high confidence by Net-Cox with network information, was validated as a biomarker for predicting early recurrence in platinum-sensitive ovarian cancer patients in laboratory." (PMID 23555212, 2013). "In particular, we identified ECM protein fibrillin-1 as a central node in ECM network, and high levels of fibrillin-1 expression in primary tumor are associated with early recurrence in platinum-sensitive ovarian cancer." (PMID 24069583, 2013). "Overall, the observations strongly support the hypothesized role of FBN1 in platinum-sensitive ovarian cancer patients." (PMID 23555212, 2013). "The plots suggest that FBN1 plays a role on platinum-sensitive ovarian cancer, and it could be developed as a target for platinum-sensitive patients with high FBN1 expression after about 12 months of the treatment." (PMID 23555212, 2013). "Similarly, FBN1 has been reported to promote ovarian cancer metastasis." (PMID 34680394, 2021). "We then measured expression of FBN1 and OR4M1 in five ovarian cell lines: one normal ovarian epithelial cell line (HOSEpiC), and four ovarian cancer cell lines namely, SKOV-3, PEO1, PEO4 and MDAH-2774." (PMID 34386072, 2021). "Methylation of FBN1 in normal ovarian tissue requires further investigation, since there is a lack of comparable normal methylation data held through TCGA and SMART for ovarian cancer." (PMID 34386072, 2021).